CLCN7 (Cl-/H+ antiporter 7)
Diseases named in the same sentence as CLCN7 in open-access papers (continued):
Sharing a sentence is not in itself a finding about the gene and the disease.
osteopetrosis (continued). "CCDC154 is mainly involved in osteopetrosis and hypoplastic left heart syndrome, and CLCN7 is mainly involved in osteopetrosis and angiogenesis." (PMID 35990977, 2022). "The second osteopetrosis form can be type I or II; both differ in the presentation of clinical features and genetic mutations located in the LRP5 and CLCN7 genes, respectively." (PMID 35163424, 2022). "This is in line with the high calcium concentrations in CLCN7-dependent osteopetrosis reported by others." (PMID 35618777, 2022). "The first indication of a role of ClC-7 in osteopetrosis came from the phenotype of ClC-7 knockout mice which recapitulated the human disease: Clcn7−/− mice showed severe osteopetrosis and retinal degeneration." (PMID 35159175, 2022). "The autosomal dominant form of osteopetrosis (ADO), i.e., Albers-Schönberg disease, is caused primarily by heterozygous mutations in the chloride channel 7 (CLCN7) gene." (PMID 33162933, 2020). "Disruption of the Clcn7 gene in mice results in severe osteopetrosis in the long bones of the extremities, shorter stature and splenomegaly." (PMID 26346547, 2016). "Two of the genes whose mutations cause osteopetrosis are CLCN7 and OSTM1, encoding the chloride-proton (Cl−/H+) exchanger ClC-7 and its obligate β-subunit Ostm1 (osteopetrosis-associated transmembrane protein 1)." (PMID 24159188, 2014). "The molecular and genetic evaluation demonstrated the involvement of CLCN7, one of the main gene responsible of malignant osteopetrosis." (PMID 25410126, 2014). "Heterozygosity for CLCN7 variants is found in patients with more benign autosomal-dominant osteopetrosis (ADO) without neurodegeneration (Albers-Schönberg disease, ADO II) (MIM: 166600)." (PMID 38838776, 2024). "Furthermore, ADO II caused by CLCN7 mutation accounts for 70% of ADO, which was the most common type of osteopetrosis." (PMID 40018371, 2024). "Moreover, the chloride channels CLCN3 and CLCN7 are known to participate in bone resorption because CLCN7 ablation leads to osteopetrosis in humans and CLCN3 contributes to organelle acidification in mice." (PMID 38395460, 2024). "Surprisingly, patients carrying this variant lacked osteopetrosis, the hallmark of “classical” CLCN7 disease." (PMID 38838776, 2024). "There are many genetic studies on osteopetrosis, but currently, no serum metabolic research has been found on osteopetrosis caused by CLCN7 mutations." (PMID 40018371, 2024). "Osteopetrosis is characterized by increased bone density caused by decreased osteoclasts or dysfunction of their differentiation and absorption properties, usually caused by biallelic variants of the TCIRG1(OMIM:604592)and CLCN7(OMIM:602727) genes." (PMID 36999084, 2023). "A somewhat surprising finding was that several, mostly dominantly inherited, CLCN7 variants causing osteopetrosis (but not neurodegeneration) produce a significant acceleration of gating kinetics." (PMID 37374100, 2023). "Additionally, disease candidate gene sequencing via Sanger sequencing in further two families (OP5 and OP9) with osteopetrosis identified two homozygous variants, one each in TCIRG1 and CLCN7." (PMID 34753502, 2021). "OPTA2 (MIM166600, eponymously known as Albers-Schönberg disease) is caused by CLCN7 mutations." (PMID 33193107, 2020). "In this study, we derived and expanded iPSC lines successfully from osteopetrosis patients with mutations in TCIRG1, CLCN7 and SNX10 genes (accounting nearly 70% of all cases) using two different integration-free reprogramming methods under feeder-free culture conditions." (PMID 31315669, 2019). "The most commonly affected genes of osteopetrosis are CLCN7 and TCIRG1." (PMID 26346547, 2016). "A spontaneous autosomal recessive osteopetrosis mouse model with the mutant allele in Clcn7 locus displayed no tooth eruption or tooth root formation." (PMID 26829236, 2016).
osteopetrosis (continued). "In the remaining ~30% of cases, no mutations in CLCN7 gene sequences were found, suggesting involvement of further genes in the pathogenesis of this form of osteopetrosis." (PMID 25873953, 2015). "Interestingly, not all osteopetrosis-causing CLCN7 mutations from patients are associated with a loss of ion transport." (PMID 38136669, 2023). "Of these models, the oc/oc, Clcn7−/−, and gl/gl mice carry mutations in the genes with the highest incidence in human IMO (Tcirg1, Clcn7, and Ostm1, respectively) and thus most substantially facilitated study of the pathophysiology of the most severe forms of human osteopetrosis." (PMID 33575431, 2021). "However, in contrast to Clcn7unc/unc mice, the osteopetrosis of Clcn7td/td mice was as pronounced as in Clcn7−/− mice, but intriguingly their neuropathy with lysosomal storage and neurodegeneration was less severe and no accumulation of autophagic material was detected." (PMID 33708769, 2021). "Mutations of CLCN7 cause a family of osteopetroses of differing ageof presentation and severity, including infantile malignantCLCN7-related recessive osteopetrosis (ARO), intermediate autosomalosteopetrosis (IAO), and autosomal dominant osteopetrosis type II (ADOII,Albers-Schoenberg disease)." (PMID 21533022, 2011). "The spectrum of CLCN7-related osteopetrosis includes infantile malignant CLCN7-related ARO, IAO and ADOII.CLCN7 (13%–16%) and TCIRG1 (51%–53%) are the major obligate genes responsible for ARO." (PMID 36999084, 2023). "HSCT is also used to treat genetic abnormalities in CLCN7, TCIRG1, SNX10, and TNFRSF11A leading to osteopetrosis." (PMID 33350578, 2021). "In contrast to other gene defects described in osteopetrosis (TCIRG1, CLCN7), OSTM1 mutations are typically not curable by a curative hematopoietic stem cell transplantation because of their early and irreversible neurological involvement." (PMID 40625472, 2025). "Clcn7unc/unc mice, in which ClC-7 is converted into a pure chloride conductor, show a milder osteopetrosis phenotype with no changes in the fur color, but they develop lysosomal storage disease and neurodegeneration similar to Clcn7−/− mice." (PMID 38027030, 2023). "Clcn7unc/unc mice, in which ClC-7 functions as a pure Cl− conductor due to the E245A mutation of its “gating glutamate” did not display a fur color phenotype and they presented an osteopetrosis that was milder than in Clcn7−/− mice." (PMID 33708769, 2021). "Mutations in genes TCIRG1, CLCN7, OSTM1, SNX10 and PLEKHM1 lead to osteoclast rich osteopetrosis, which has abundant but nonfunctional osteoclasts." (PMID 34753502, 2021). "In this study, an affected girl with osteopetrosis was introduced who had no mutation in most common causative genes (TCIRG1, CLCN7 and OSTM1) for the disease, but analysis of SNX10 gene was able to detect a novel homozygous deletion in her." (PMID 29090071, 2017). "A recently reported de novo CLCN7 mutation (p.Tyr715Cys) causes widespread severe lysosome pathology (hypopigmentation, organomegaly, and delayed myelination and development, “HOD syndrome”), but no osteopetrosis." (PMID 38838776, 2024). "With this work we contribute to the molecular dissection of the CLCN7 deficient ARO and provide new insights into the molecular bases of the disease which can be exploited for the molecular diagnosis of malignant osteopetrosis with an inconsistent clinical history and a not clear phenotype." (PMID 25410126, 2014).
autosomal recessive osteopetrosis (16 papers, 2013 to 2025). An autosomal recessive form of osteopetrosis caused by mutation(s) in at least 8 genes related to osteoclast function. "The involvement of ClC-7 in bone resorption was confirmed by the presence of CLCN7 mutations in a human patient with malignant osteopetrosis." (PMID 37374100, 2023). "Compound heterozygous variants in CLCN7 are interestingly known to cause autosomal recessive osteopetrosis." (PMID 34777883, 2021). "Recently, long-term survival in infantile malignant autosomal recessive osteopetrosis secondary to homozygous p.Arg526Gln mutation in CLCN7 was described." (PMID 23160729, 2013). "In addition, mutations in the vacuolar-H+-ATPase (TCIRG1) and chloride channel-7 (CLC-7; also known as CLCN7) lead to autosomal recessive osteopetrosis due to aberrant lysosomal activity in osteoclasts and consequent defects in bone resorption." (PMID 38294065, 2024). "In humans, autosomal recessive osteopetrosis (ARO) is mainly (in >70% cases) associated with mutations in two genes: TCIRG1, encoding the α3 subunit of v-ATPase, and CLCN7, encoding anion transporter CLC-7 that works with v-ATPase to acidify the bone while maintaining electroneutrality." (PMID 33081155, 2020). "At variance with autosomal recessive osteopetrosis, CLCN7-dependent ADO2 is not life threatening but can be seriously debilitating." (PMID 26325626, 2015).
autosomal dominant osteopetrosis type 2 (15 papers, 2010 to 2023). "Autosomal-dominant osteopetrosis type II (ADOII) is most often caused by mutation of the CLCN7 gene leading to impaired bone resorption." (PMID 35618777, 2022). "Severe neonatal or infantile forms have the worst prognosis, while CLCN7 variants causing osteopetrosis late‐onset form type 2 (OPTA2) (formerly autosomal dominant type II osteopetrosis (ADOII) have a varied clinical phenotype, including asymptomatic forms." (PMID 34539568, 2021). "The autosomal dominant form of the disease (autosomal dominant osteopetrosis type 2 [ADO2]) is caused by single allele dominant negative mutations of the CLCN7 gene, encoding the ClC-7 chloride transporter indispensable for the mechanism of bone resorption." (PMID 37680985, 2023). "Autosomal dominant osteopetrosis type II (ADO II), characterized by increased bone mass and density, is caused by mutations in the chloride channel 7 (CLCN7) gene." (PMID 33304905, 2020). "In about 70% of patients affected by autosomal dominant osteopetrosis type 2 (ADO2), osteoclast activity is reduced by heterozygous mutations of the CLCN7 gene, encoding the ClC-7 chloride/hydrogen antiporter." (PMID 26325626, 2015). "Autosomal dominant osteopetrosis type 2 (ADO2), or Albers-Schönberg disease, is a genetic bone condition due, in roughly 70% of patients, to heterozygous missense mutations of the CLCN7 gene." (PMID 26325626, 2015). "When tested via single intraperitoneal injection in pre-puberal autosomal dominant osteopetrosis type 2 (ADO2) mice, carrying a heterozygous mutation of the Clcn7 gene (Clcn7G213R), sshLNP, this significantly downregulated the Clcn7G213R related mRNA levels in femurs at 48 h." (PMID 37680985, 2023). "The G215R mutation in CLCN7, for example, leads to autosomal dominant osteopetrosis type 2 that does not abolish the transport function of the channel but rather causes a severe trafficking defect with the G215R-CLCN7 mutation rendering CLCN7 retention in the ER." (PMID 33718388, 2021).
osteoporosis (12 papers, 2010 to 2025). A condition of reduced bone mass, with decreased cortical thickness and a decrease in the number and size of the trabeculae of cancellous bone (but normal chemical composition), resulting in increased fracture incidence. "Loss of the chloride channel (CLCN7) in humans leads to inefficient acidification of bone and leads to osteoporosis." (PMID 30943394, 2019). "Results of subsequent experiments with various Clcn-7 mutant mice showed that the phenotypes of neurodegenerative disease and osteoporosis are independent outcomes caused by defects in lysosomal- and ruffled border-localized CLC7, respectively, rather than secondary to each other." (PMID 37111358, 2023). "Advances in GWAS have identified hundreds of susceptibility loci for osteoporosis and low BMD, for example, mutations in genes CLCN7, GALNT3, IBSP, LTBP3, RSPO3, and SOX4." (PMID 41393297, 2025). "Additionally, genes associated with rare monogenic forms of osteoporosis, such as SOST, CLCN7, and LRP5, have also been reported to influence BMD variation in diverse population studies." (PMID 41393297, 2025). "Inhibitors of CLCN7 have been investigated for treatment of osteoporosis." (PMID 37363915, 2023). "This is not the first time that common variation within a gene that has previously been identified as underlying a rare monogenetic form of osteoporosis and/or high bone mass has been implicated in BMD regulation, other examples including the SOST, CLCN7 and LRP5 genes." (PMID 24176111, 2013). "Similarly, given the high expression levels of CLCN7 in OCs and its indispensable role in bone homeostasis, CLCN7 has also received considerable attention as a potential therapeutic target for the treatment of osteoporosis." (PMID 33718388, 2021). "These mice exhibited the same severe osteoporosis phenotype as the Clcn7−/− mice, but the fur color was not affected." (PMID 37111358, 2023).
autosomal dominant osteopetrosis (8 papers, 2016 to 2024). Autosomal dominant form of osteopetrosis (disease). "In our first case with autosomal dominant osteopetrosis mutation in CLCN7 gene, c.856C > T was found, a likely pathogenic variant." (PMID 34777883, 2021). "Autosomal dominant osteopetrosis is caused by monoallelic mutations in the CLCN7 gene, which is called IOP." (PMID 34266467, 2021). "Thus, we identified a CLCN7 mutation in a family with autosomal dominant osteopetrosis, RTA, renal stones, epilepsy, and blindness." (PMID 27540713, 2016). "In summary, we have successfully genotyped an autosomal dominant osteopetrosis family and generated ADO2-iPSCs with the known mutation CLCN7 (R286W) from the urine cells of ADO2 patients." (PMID 31412925, 2019).
osteosclerosis (5 papers, 2016 to 2026). Abnormally high bone density. "Variants in the CLCN7 gene cause osteosclerosis, a condition marked by impaired osteoclast function." (PMID 40276109, 2025). "Gene mutations such as mutations in the ClCN7 genes can be responsible for osteosclerosis and these mutations are generally identified by presence of unerupted tooth." (PMID 27148461, 2016).
retinal degeneration (5 papers, 2010 to 2022). Degeneration of the retina. "Mice with a disruption of the corresponding gene CLCN7 showed severe OP, retinal degeneration, and they only live for between five and seven weeks." (PMID 23302420, 2013).
anemia (3 papers, 2011 to 2025). A reduction in the number of red blood cells, the amount of hemoglobin, and/or the volume of packed red blood cells. "Previously, two homozygous missense mutations of CLCN7 segregating in cis in a Pakistani family with ARO was reported to exhibit dysmorphic facies, mild anemia, brain atrophy and bilateral optic atrophy." (PMID 34753502, 2021). "CLCN7 variants can also cause ARO, presenting early with severe symptoms like bone marrow failure, and IAO with milder symptoms such as minor trauma fractures and moderate anemia." (PMID 40276109, 2025).
epilepsy (3 papers, 2016 to 2025). A brain disorder characterized by episodes of abnormally increased neuronal discharge resulting in transient episodes of sensory or motor neurological dysfunction, or psychic dysfunction. "Neither CLCN7 nor CA2 mutations have previously been reported to be associated with renal stones or epilepsy." (PMID 27540713, 2016). "Samples from individuals III.17 and IV.11 with OPT and epilepsy were not available to investigate for such digenic inheritance of epilepsy and OPT, which was due to the CLCN7 mutation." (PMID 27540713, 2016).
bone marrow failure (2 papers, 2017 to 2025). "The phenotype of IARO, previously associated with mutations in the PLEKHM1, CLCN7, and CA2 genes, 21, 24, is defined as asymptomatic at birth, with patients exhibiting fractures by the end of their first decade of life, while bone marrow failure and hepato-splenomegaly are rare." (PMID 28592808, 2017).
lentivirus infection (2 papers, 2016 to 2023). Virus diseases caused by the Lentivirus genus. "After lentivirus infection or siRNA transfection, the expression of Clcn7 in ameloblast LS8 and odontoblast-like MDPC-23 cells was downregulated." (PMID 26829236, 2016). "After 3 days of lentivirus infection, obvious GFP fluorescence could be detected in the infected tooth germs, meanwhile, the Clcn7 mRNA level was decreased about 70% in the Clcn7-shRNA treated group, compared to the negative-shRNA group (P = 0.0001, data not shown)." (PMID 26829236, 2016).
neuropathies (2 papers, 2021 to 2025). "An alternative explanation for the milder neuropathy of Clcn7td/td mice compared to Clcn7−/− mice was recently provided by the unexpected finding that the mutation of the “proton glutamate” to alanine does not completely abolish currents by ClC-7td." (PMID 33708769, 2021). "Activating CLCN7 mutations can cause vacuolization in patients’ tissues, but it is unclear whether this occurs in CLCN3 or CLCN4 neuropathy patients whose mutations we have analyzed here." (PMID 40169677, 2025). "Dominant CLCN7 mutations, which may lead to subcellular mislocalization of the ClC-7/Ostm1 complex or the impingement of the dysfunctional subunit on the ion transport properties of the unaffected subunit, do not lead to neuropathy in mild ADO2." (PMID 33708769, 2021).
asthma (1 paper, 2021). "TNRC6B and MET were hypermethylated in both of our ACO patients and the asthma patients in previous EWAS, while DHX30, SFXN, C19orf28, and CLCN7 were hypomethylated." (PMID 33658578, 2021).
Atrophy (1 paper, 2010). Any weakening or degeneration, especially through lack of use. "The loss of the clcn-7 gene is accompanied by severe impairment of visual function and atrophy in the neural retina, due to the loss of lysosome function in the neural retina and RPE." (PMID 20711468, 2010).
Bestrophinopathy (1 paper, 2017). "We found the same dialysis activated Cl- currents in bone marrow derived neutrophils from CLIC1, CLCN3, CLCN7 and KCC3 KO animals and in blood neutrophils from a Bestrophinopathy patient (Best1 H178P) (representative current traces)." (PMID 28553230, 2017).
leukocytosis (1 paper, 2023). "Furthermore, determining whether leukocytosis is a phenotype in CLCN7-related ARO children and identifying the underlying genotype may require a more specific cohort." (PMID 37168803, 2023). "Here, we report the natural course of a patient with CLCN7-related ARO involving scarcely leukocytosis at birth, rapidly progressing to neurological deterioration with a very poor prognosis." (PMID 37168803, 2023). "We reported a case of neonatal CLCN7-related ARO detected at birth, with an onset symptom of severe leukocytosis; later symptoms included vision and hearing loss as well as neurological deficits in the form of frequent seizures and intellectual and motor disability." (PMID 37168803, 2023).
myopia (1 paper, 2022). "Patients with mutations c.141+4A>G in the CLCN7 gene and c.2902-9C>T in the PLEKHM1 gene had multiple fractures as well as sensorineural hearing loss, myopia, arthropathies, and ligamentous apparatus lesions." (PMID 35052464, 2022).
osteomalacia (1 paper, 2016). Disorder caused by an interruption of the mineralization of organic bone matrix leading to bone softening, bone pain, and weakness. "Thus, in contrast to patients carrying TCIRG1 mutation, patients carrying CLCN7 mutation do not seem to suffer from osteomalacia." (PMID 26346547, 2016). "A novel mutation in CLCN7 (D145 G) impaired the activation and relaxation kinetics of the CLC-7 ion transporter and had no sign of osteomalacia." (PMID 26346547, 2016).
Thrombocytopenia (1 paper, 2019). A reduction in the number of circulating thrombocytes. "Previously, a case of infantile malignant CLCN7-related ARO, with neonatal thrombocytopenia was reported in Korea." (PMID 30759959, 2019).
uremia (1 paper, 2019). A clinical syndrome associated with the retention of renal waste products or uremic toxins in the blood. "ADO2 kidneys also showed elevated transcriptional expression of Clcn7, along with an increased phosphoremia, while calcemia, uremia and uricemia were normal." (PMID 31231577, 2019).